NLRP3 (NLR family pyrin domain containing 3)
Diseases named in the same sentence as NLRP3 in open-access papers (continued):
Sharing a sentence is not in itself a finding about the gene and the disease.
infection (continued). "Differences in cell culture conditions or between Y. enterocolitica and Y. pseudotuberculosis may account for the differential role of NLRP3 during infection of human IECs." (PMID 37615436, 2023). "Our current findings demonstrate that systemic immune cells in severe asthmatics may also be more responsive to infection-induced priming and subsequent NLRP3 inflammasome-mediated, steroid-insensitive inflammatory responses." (PMID 38044426, 2023). "Although the biological activities of mycolactone during infection are thought to mediate immunosuppressive effects, recent studies have shown that exposure to a low dose of mycolactone can trigger NLRP3 inflammasome activation resulting in IL-1β release from LPS-primed human macrophages." (PMID 37910490, 2023). "Important targets for miR-223 involved in infection and inflammation are NLRP3, IKKα, and NF-κB." (PMID 37895148, 2023). "Notably, Yersinia utilizes two other effectors, YopM and YopK, to evade YopE-triggered pyrin and T3SS-triggered NLRP3/caspase-11 inflammasome activation, respectively, and promote infection." (PMID 37615436, 2023). "These facts suggest that E protein suppresses NLRP3 inflammasome activation during the early stages of infection while in the later stages, it may enhance NLRP3 inflammasome activation." (PMID 36851564, 2023). "Based on in-depth studies, the inability of NLRP3 to mediate Salmonella clearance could be attributed to the multiple strategies implemented by Salmonella to inhibit NLRP3 inflammasome activation during infection." (PMID 37155697, 2023). "We found that CVB3 pre-infection could significantly inhibit the production of IL-1β and the expression of NLRP3 in the small intestine." (PMID 37243164, 2023). "The reduced activity of UCH-L5 might result in suppressing activation of NLRP3 inflammasome in the early phase of infection." (PMID 37841261, 2023). "NLRP3‐targeted therapies may thus require dosing that will allow an effective immune response during infection to reduce viral burden while lessening chronic, detrimental inflammation later in infection." (PMID 37360982, 2023). "ROS can activate signaling pathways, such as NLRP3 inflammasome, that lead to the production of antiviral cytokines and chemokines, promoting an inflammatory response and recruiting immune cells to the site of infection." (PMID 38047681, 2023). "Furthermore, endogenous coimmunoprecipitation experiments showed that PmCQ2 infection induced the interaction of RACK1 with NLRP3 and NEK7 in macrophages." (PMID 37684678, 2023). "Herein, we focused on the role of CVB3 in macrophages and found that CVB3 pre-infection in macrophages could significantly inhibit LPS-induced NLRP3 inflammasome activation and IL-1β production." (PMID 37243164, 2023). "Therefore, it can be concluded that the presence of LRV1 dampens NLRP3 activation to favor infection and pathogenesis of Leishmania parasite." (PMID 38097942, 2023). "However, some evidence shows that NLRP3 inflammasome activation can be detrimental during the course of infection, being responsible for high levels of pro-inflammatory cytokines." (PMID 37508374, 2023). "NLRP3 formation is triggered by a range of substances generated during infection, tissue damage, and metabolic imbalances; however details of NLRP3 activation by events at the plasma membrane remain unclear." (PMID 37158595, 2023). "The NOD, LRR, and pyrin domain-containing protein 3 (NLRP3/NALP3) inflammasome is an intracytoplasmic sensor that assembles into a protein complex within inflammatory cells upon infection (PAMPs) or tissue damage (DAMPs), leading to maturation of inflammatory cytokines such as IL-18 and IL-1β." (PMID 36777741, 2023). "More importantly, SiiD was required for SE to reduce the gut inflammation and evade host immune clearance mediated by NLRP3 inflammasome in vivo, which might be essential for bacterial colonization during long-term infection." (PMID 37155697, 2023).
infection (continued). "That study also demonstrated that NLRP3 is activated to limit the infection by SARS-CoV-2 as its inhibition with MCC950 led to the release of the virus by infected macrophages, presumably via inhibition of pyroptosis, since that would sustain the macrophage to allow for more viral replication." (PMID 36661317, 2023). "Expression of genes within the periapical lesion after 14 days of infection was confirmed with real time PCR, where nociceptor-ablation resulted in a significant upregulation of IL1a (p = 0.01), Tnf (p = 0.01), and Nlrp3 (p < 0.01), whereas ablated mice had reduced expression of Alox5 (p = 0.03)." (PMID 37845223, 2023). "The mutant S. aureus ALC837 infection was unable to induce caspase-1 activation under identical conditions, demonstrating that α toxin is needed for the S. aureus-induced activation of the NLRP3 inflammasome." (PMID 38089811, 2023). "Interestingly, in the first phase (up to day 3 post-infection), the expression of NLRP3, IL-1β, and IL-18 was significantly upregulated in several organs before viremia was detectable in blood." (PMID 36800238, 2023). "Therefore, hvKp and cKp infections enhance the occurrence of pyroptosis via the formation of NLRP3 inflammasome in BMDMs." (PMID 37457695, 2023). "However, insufficient activation of the NLRP3 inflammasome prevents the organism from responding to the virus invasion, facilitating the survival of harmful microorganisms and resulting in infections and diseases." (PMID 38249297, 2023). "The NLRP3 inflammasome is a critical component of the innate immune system mediating caspase-1 activation and proinflammatory cytokines secretion in response to harmful stimuli such as infection and endogenous stress." (PMID 36779699, 2023). "As lysosomal cathepsin B is involved in NLRP3 inflammasome activation, we examined whether cathepsin B activity contributes to the elevated NLRP3 inflammasome formation and pyroptosis during infection." (PMID 37457695, 2023). "The results of this study indicated a pivotal role of NLRP3 in eliminating IV infections." (PMID 37773712, 2023). "However, the detailed mechanisms that trigger the assembly of the NLRP3 inflammasome upon infection of these viruses remain unresolved." (PMID 37515138, 2023). "Additionally, ERS inhibitor TUDCA infection can prevent NLRP3 inflammasome activation and pyroptosis in BCG-infected THP-1 macrophages." (PMID 37511451, 2023). "Furthermore, WB results showed that WT W24 infection activated the NLRP3 inflammasome, while the degree of inflammasome activation was significantly reduced in W24Δhcp1-infected kidneys, which was consistent with the IHC results." (PMID 36977062, 2023). "NLRP3 is activated to limit the infection by SARS-CoV-2 as its inhibition with the small molecule MCC950 led to the release of the virus by infected macrophages, presumably via inhibition of pyroptosis, since that would sustain the macrophage to allow for more viral replication." (PMID 36661317, 2023). "infection does not cause ubiquitous increases in IL-1β, malarial hemozoin induces IL-1β secretion via activation of the NLRP3 inflammasome." (PMID 37375100, 2023). "The data obtained show that M. furfur activates the inflammasome by inducing the expression of Il-1β, Caspase-1, IL-18, and NLRP-3 after 4 h of infection, while the simultaneous addition of L. plantarum totally inhibits this activation, bringing them back to the control values." (PMID 38132754, 2023). "Furthermore, as demonstrated in an A. fumigatus mouse infection model, inflammasome activation via NLRP3 eventually provides immune protection and IL-1β-mediated survival." (PMID 36983500, 2023). "NLRP3 modulation might therefore be a promising intervention to balance a functional immune response for infection control of different viruses." (PMID 36800238, 2023).
infection (continued). "While we observed that inhibition of NLRP3 reduced IL-1β secretion during infection with ST, cell death and IL-1β secretion by Xiap−/− cells was still higher than WT cells, suggesting that XIAP inhibits additional cell death pathways to control cell death and IL-1β secretion by APCs." (PMID 37347786, 2023). "Followed by the envelope protein, SARS-CoV-2 E protein, which depends on ROS and K+ extravasation, may initially suppress the host NLRP3 inflammasome response to viral RNA, while possibly increasing the NLRP3 inflammasome response later in infection." (PMID 37868953, 2023). "This study investigated whether ERS is involved in NLRP3 inflammasome activation and pyroptosis after infection of THP-1 macrophages with BCG." (PMID 37511451, 2023). "Furthermore, knockdown of RACK1 significantly inhibited the secretion of IL-1β and TNF-α as well as the transcription of NLRP3 and IL-1β during PmCQ2 infection." (PMID 37684678, 2023). "NLRP3 inflammasome, which is the most widely studied, has been proved to play an important role in the immune responses against bacteria, virus, fungi and parasite infections mainly through indirect recognition." (PMID 37817895, 2023). "NLRP3 inflammasome plays a pivotal role in protecting the host from infection." (PMID 36875122, 2023). "This prolonged exposure of epithelial cells may contribute to the secretion of proinflammatory cytokines such as IL-1 beta in response to infection by the influenza virus through an NLRP3-dependent mechanism." (PMID 37803025, 2023). "Moreover, endogenous Co-IP experiment using anti-2B antibody also verified that ECHO 11 2B interacted with NLRP3 in THP-1 macrophages in the context of ECHO 11 infection." (PMID 36026486, 2022). "We knocked down NLRP3 expression in TM4 cells by infection with siRNA targeting NLRP3 (siNLRP3)." (PMID 35915511, 2022). "From this data, we can conclude that the expression of NLRP3 in mice has a protective effect on induced periodontal bone loss only in the absence of infection." (PMID 35281020, 2022). "The transcriptional regulation mechanism of NLRP3 expression elevation after exogenous infection stimulation remains unclear." (PMID 35611792, 2022). "Moreover, Ly-6G immunofluorescence staining was used to measure neutrophil infiltration after NLRP3 knockdown at 3 d after infection." (PMID 35463001, 2022). "The activation of the pyroptosis route has been demonstrated by studying two proteins associated with the inflammasome, i.e., pyrin domain containing 3 (NLRP3) and IL-1β, after infections in mice and murine macrophages with A. hydrophila and A. veronii, respectively." (PMID 35874671, 2022). "On farm B, the App-specific antibody response was significantly lower for the NLRP3-2906AG genotype than for the NLRP3-2906AA genotype, suggesting that NLRP3-2906G might contribute to inhibiting infections such as App." (PMID 36428390, 2022). "Additionally, numerous studies have shown that the NLRP3 inflammasome is involved in cellular inflammatory responses and helps to recognize pathogen infection, thereby promoting the maturation of IL-1β and IL-18 in macrophages." (PMID 36430657, 2022). "The mechanism is that these medicinal plants and their active derivatives can inhibit NLRP3 inflammasome in Mtb-infection models at transcriptional and post-transcriptional levels, so they can be used as host-directed adjuvants to control excessive inflammation induced by Mycobacterium tuberculosis." (PMID 36248872, 2022). "Additionally, NLRP3 activation was shown by infection with RNA and DNA viruses, such as influenza virus, adenovirus and respiratory syncytial virus." (PMID 35369454, 2022). "In addition, quantitative real-time PCR assay of EV71 replication was applied in WT/KD cells at different times after infection, results confirmed that both NLRP3/Caspase-1 and cellular EV71 replications increased rapidly with the increment of exposure time." (PMID 35807435, 2022).
infection (continued). "Second, upregulation of inflammasomes and particularly the NLRP3 inflammasome in response to infection might contribute to anti-infective pyroptosis." (PMID 36240188, 2022). "Recent studies have shown that renal inflammation can activate NLRP3 inflammatory vesicles, which trigger innate immune defenses via pro-inflammatory cytokines such as IL-1β in response to signals such as infection and metabolic dysregulation." (PMID 35873572, 2022). "For instance, the components of inflammatory pathways that are major therapeutic targets like NF-κB, TNFα, and the NLRP3 inflammasome are shared across many cell types and mediate cellular processes from cell survival to host defence against infection to chronic inflammatory disease." (PMID 36339576, 2022). "Upon infection MAVS promotes NLRP3 inflammasome activation, which influences immune responses." (PMID 36300112, 2022). "Our previous study has shown that P. multocida activates NLRP3 inflammasome, subsequently induces caspase-1 activation which process pro-IL-1β into biologically active IL-1β, leading to IL-1β secretion and inflammatory response against infection." (PMID 35350616, 2022). "Thus, the knockdown of inflammatory components of NLRP3 decayed IL-1β activation during SVA infection." (PMID 35254168, 2022). "Moreover, infection of Nlrp3-/- BMDMs with Δvprh bacteria carrying pAts3 resulted in reduced cell death compared to that observed upon infection of BMDMs generated from WT mice." (PMID 36155655, 2022). "In addition, targeting the NLRP3 inflammasome (e.g., MCC950) or downstream IL1β (e.g., Canakinumab) has raised concerns over increased susceptibility to pathogenic infection and long-term side effects." (PMID 35054783, 2022). "Furthermore, genetic deletion of CB2R amplified the NLRP3 activation post-PA infection, besides the observation of higher levels of NLRP3, ASC, and caspase-1(p20) levels in the lungs of CB2KO mice." (PMID 36463179, 2022). "As a consequence, the SARS-CoV-2 E protein may reduce the host NLRP3 inflammasome response to viral RNA at early stages of the infection while possibly enhancing NLRP3 inflammasome responses later on." (PMID 35847031, 2022). "Therefore, infection of PCV2 and PRV caused NLRP3-mediated cellular inflammatory reaction, and the coinfection of PCV2 and PRV aggravated the inflammation." (PMID 35457287, 2022). "However, one mechanism employed by the inflammasome to protect against intratracheal infection is NLRP3/ASC secretion of IL-1β and IL-18." (PMID 35626718, 2022). "Overall, our results suggest that NLRP3/GSDMD pathway mediated-pyroptosis in the lungs may be a key event in this process and provide new insights into the underlying mechanism of infection." (PMID 35761358, 2022). "ECHO 11 infection triggered NLRP3 inflammasome activation and pyroptosis in THP-1 and mice BMDMs." (PMID 36026486, 2022). "Inhibition of abnormal ceramide generation or blockade of NLRP3 activation may repress HCC development after OBI infection." (PMID 36058909, 2022). "However, infection of Nlrp3-/- BMDMs resulted in delayed cell death and ~60% reduction in the calculated AUC." (PMID 36155655, 2022). "Since neutrophils can prime NLRP3 inflammasome through bacterial- and host-derived molecules, the host is able to engage innate immunity upon direct or indirect contact with bacteria whatever the site of infection." (PMID 35406754, 2022). "Cell viability was measured with an MTT assay in NLRP3 KD cells after infection." (PMID 35446851, 2022). "To test how the mutations on M2 would impact the ability of the virus to induce IL-1β because of NLRP3 activation, we conducted an NLRP3 reconstitution assay followed by infection as well as PAMs infection with the respective virus and measured the production of IL-1β." (PMID 35062292, 2022).
infection (continued). "Therefore, to explore the role of K+ efflux in PmCQ2-induced NLRP3 inflammasome activation, different K+ channel inhibitors including KCl, Quinine and Glibenclamide were used to pretreat macrophages prior to infection to inhibit potassium efflux." (PMID 35350616, 2022). "Upon infection with SARS-CoV-2 the innate immune system recognizes both Pathogen- and Damage- Associated Molecular Patterns (PAMPs and DAMPs, respectively) and responds by activating the NLRP3 (NOD-, LRR-and pyrin domain-containing protein 3) inflammasome." (PMID 36742994, 2022). "The NLRP3 inflammasome is a multiprotein complex that regulates caspase‐1 activation and subsequent interleukin (IL)‐1β and IL‐18 release from innate immune cells in response to infection or injury." (PMID 35137954, 2022). "During infection, NLRP3 is the primary producer of IL-1β and IL-18." (PMID 35626718, 2022). "Inflammasomes regulate the activity of caspase-1 and the maturation of IL1β and IL-18, which act as innate immune system sensors and receptors in various infections, cancer, and other diseases, among which the NLRP3 inflammasome has been well characterized to date." (PMID 35457287, 2022). "NLRP3 is phosphorylated by Spleen tyrosine kinase (Syk), Death-associated protein kinase (DAPK), Transforming growth factor beta-activated kinase 1 (TAK1) and Extracellular Signal-Regulated Kinase 1 (ERK1) in infection models." (PMID 35663964, 2022). "It appears that NLRP3 is protective, as mice lacking NLRP3 were more susceptible to infection as compared to wild-type (wt) animals." (PMID 35369454, 2022). "When microglial cells face a pathogen, for instance Streptococcus pneumoniae, a microorganism whose infections produce meningitis, they respond by assembling inflammasome NLRP3, activating caspase-1, secreting IL-1β and IL-18 and inducing cell death by pyroptosis." (PMID 35783102, 2022). "In addition to ESX-1, ESX-5 secreted substrates also play a role in activation of NLRP3 inflammasome in response to infection with Mmar." (PMID 35237260, 2022). "In this study, SFTSV infection induced processing of pro-caspase-1 and subsequent maturation and secretion of IL-1β/IL-18 were significantly suppressed in human PBMCs when NLRP3 gene was knocked down by specific shRNA or inhibited by a specific inhibitor, glibenclamide." (PMID 35173184, 2022). "Infection-induced OXSR1 may suppress protective NLRP3 inflammasome responses and downstream IL-1β/TNF-α production." (PMID 35545295, 2022). "STING-mediated IFN production may also polarize macrophages towards an anti-inflammatory response, which, while advantageous for bacteria persistence, could also potentially decrease the pro-inflammatory environment induced in long-term infections by NLRP3." (PMID 35626718, 2022). "Since hamster fibroblasts are major constituents of the HCP stroma, low-level expression of NLRP3 may favor intracellular parasite outgrowth early in infection." (PMID 35215131, 2022). "SARS‐Cov‐2 E protein may inhibit the host NLRP3 inflammasome response to viral RNA in the early stage of infection, but it will increase NLRP3 inflammasome response in the later stage of infection, and eventually induce severe inflammatory response." (PMID 36444628, 2022). "The fact that we only observed increased TNFα localised to sites of infection, and not throughout the whole embryo, suggests that oxsr1a knockdown primes cells for NLRP3 activation but does not cause excess systemic inflammation." (PMID 35545295, 2022). "In addition, AIM2 knockout mice are more susceptible to Brucella infection and infection of C57BL/6, NLRC4, NLRP3, AIM2, ASC and Caspase-1 KO (knockout) BMDM (bone marrow-derived macrophage) with B. abortus than wild-type control mice." (PMID 36068262, 2022). "Furthermore, ECHO 11 infection triggered NLRP3 inflammasome activation, as evidenced by cleavages of GSDMD, pro-IL-1β and pro-caspase-1, and the release of LDH." (PMID 36026486, 2022).